AQP9 (aquaporin 9)
Diseases named in the same sentence as AQP9 in open-access papers (continued):
Sharing a sentence is not in itself a finding about the gene and the disease.
tumor (continued). "We found dramatically increased AQP9 mRNA expression in ccRCC samples: 97.9% of ccRCC patients had higher levels of AQP9 expression in tumor tissues than normal tissues." (PMID 31703694, 2019). "Although some members of the AQP family were demonstrated to be carcinogenic in many neoplasms, the prognostic value of AQP9 in ccRCC had remained to be elucidated." (PMID 31703694, 2019). "The identification of AQP9-induced tumor sensitivity to 5-FU highlights the role of AQP9 in regulating chemosensitivity in CRC." (PMID 28640255, 2017). "To further determine the clinical relevance, we analyzed the AQP9 expression in tumor tissue microarray from 367 stage II and III CRC patients by immunohistochemical (IHC) staining." (PMID 28640255, 2017). "The endpoint xenograft tumor weight was significantly lighter in the AQP9-eGFP+ tumors than the eGFP+ tumors (P < 0.01)." (PMID 27329843, 2016). "Meanwhile, AQP9 knockdown downregulated bcl-2 expression and induced activation of bax and caspase-3, suggesting that AQP9 knockdown reduced proliferation and increased apoptosis which contributed to its suppressive effect on tumor growth." (PMID 27187384, 2016). "Histopathological examination showed that the tumor cells retained expression of eGFP and the AQP9-eGFP+ tumor cells kept the cytoplasmic membrane-localization of eGFP." (PMID 27329843, 2016). "Other CpGs are associated with genes related to immune function, including T cell regulation and inflammation, tumor initiation and angiogenesis (EBI3), while other genes have been implicated in cancer aggressiveness (AQP9, RIN1)." (PMID 25472429, 2014). "AQP9, on the other hand, is highly expressed in tumor stem cells, which are found in the tumor mass and are resistant to most available treatments." (PMID 25565956, 2014). "In tumour tissue, aqp4 expression was the most abundant (6.75 ± 2.86), but there was nearly as much aqp9 (5.37 ± 4.62) (mean ± SEM, n = 6, relative to aqp1 set to 1)." (PMID 22262958, 2012). "Aqp9 is highly increased in both tumour progenitor and differentiated derivatives when compared to normal rat tissue-derived cells." (PMID 22262958, 2012). "Aqp9 is many times more highly expressed by tumour stem cells and their differentiated progeny than is the case in normal rat-derived cells." (PMID 22262958, 2012). "When comparing the expression of aquaporin 9 by the tumour stem cells to that obtained directly from tissue, aqp9 was increased with respect to tissue, while aqp 1 and 4 were decreased." (PMID 22262958, 2012). "As there seemed to be an inconsistency of expression of aqp9 at message level compared to immunolabeling of protein in the case of tumour progenitors, we carried out Western blot experiments of proteins extracted from progenitors and differentiated cells." (PMID 22262958, 2012). "In the tumour progenitor population, aqp9 was markedly more highly expressed, whilst in tumour-derived differentiated cells, aqp4 was downregulated." (PMID 22262958, 2012). "Among the tumour stem cells, aqp9/18S was measured to 19.9 ± 6.35, whereas similar ratios for aqp1 and 4 were less, 0.02 ± 0.01 and 0.04 ± 0.18, respectively (mean ± SEM, n = 7, relative to aqp1 expression in tumour set to 1)." (PMID 22262958, 2012). "In human astrocytic tumours AQP9 expression were both increased compared with normal brain tissue for all grades of astrocytic tumours and that expression was greater in high-grade tumours than in low-grade ones." (PMID 21119878, 2010). "Similarly, AQP9 regulates the tumor microenvironment in kidney cancer, hepatocellular carcinoma and colon cancer, where it modulates the polarization of tumor-associated macrophages." (PMID 39941100, 2025). "We also examined the expression of CEBPB and AQP9 in the tumor tissues by immunohistochemistry." (PMID 35590355, 2022).
tumor (continued). "The aquaporin 9 (AQP9) is a member of the aquaporin family that acts as a water-selective membrane channel, and it may be involved in cell migration, angiogenesis, and tumor growth." (PMID 34804972, 2021). "Coincidentally, it also has been reported that AQP9 may be involved in cell migration, angiogenesis, and tumor growth." (PMID 34804972, 2021). "Furthermore, it can be inferred from the results of Wilcoxon rank sum test that the expression of AQP9 in tumor samples is significantly higher than that in normal samples." (PMID 34804972, 2021). "Therefore, the connection between the expression level of AQP9 in tumor cell and TME was researched subsequently." (PMID 34804972, 2021). "It seemed that AQP9 could not only predict the clinical prognosis for tumor patients, but also be used as an indicator for the clinical treatment effect, providing directions for further improving the prognosis of patients." (PMID 33247170, 2020). "However, the relationship between AQP9 and tumor-infiltrating cells, and its prognostic value in cancers still require comprehensive understanding." (PMID 33247170, 2020). "Further studies should be conducted to explore whether AQP9 can promote the uptake of specific drugs by tumor cells based on its own transport properties to enhance the sensitivity of chemotherapy." (PMID 33247170, 2020). "In addition, the innovational aspect of this study clarified the significant correlations between AQP9 expression and various tumor-infiltrating immune cells in breast, colon, lung and gastric caners." (PMID 33247170, 2020). "Our findings revealed that SKL2001 could reverse the effects caused by overexpressed AQP9 during the development of HCC, suggesting AQP9 may function as a tumor suppressor via suppressing Wnt/β-catenin signaling." (PMID 31969493, 2020). "The results indicated that AQP9 may regulate tumor immunity by affecting correlated genes and immune related pathways." (PMID 33247170, 2020). "We further explored the potential mechanisms that AQP9 might participate in the regulation of tumor infiltration." (PMID 33247170, 2020). "Moreover, the correlations of AQP9 expression with the gene markers for immune cells indicated the potential function of AQP9 in regulating the tumor immunology of BRCA, COAD, LUAD, LUSC and STAD." (PMID 33247170, 2020). "We further investigated the mechanisms that AQP9 might participate in the regulation of tumor immunity through the network of the immune genes in correlation with AQP9." (PMID 33247170, 2020). "In our study, overexpressed AQP9 reduced the levels of DVL2, p-GSK-3β, CyclinD1 and β-catenin, suggesting that AQP9 could be a novel tumor suppressor by suppressing Wnt/β-catenin signaling pathway." (PMID 31969493, 2020). "Further studies are eagerly needed to illuminate whether AQP9 serves as a significant factor that mediates tumor metastasis through immune infiltrating cells." (PMID 33247170, 2020). "In addition to water transport, AQP9 was also involved in the occurrence and development of various tumors, promoting the proliferation, migration and invasion of tumor cells." (PMID 33247170, 2020). "To assess the level of AQP9 protein expression in FUSCC tumor samples, we performed IHC staining and found significant elevated AQP9 expression in terms of density and intensity in ccRCC tissues compared with adjacent normal kidney tissues in FUSCC cohort (p < 0.001)." (PMID 31703694, 2019). "Thus, here we used the TCGA database to evaluate the differential AQP9 expression between tumor and normal tissues, and we validated the prognostic value of AQP9 in the FUSCC cohort with long follow-up information." (PMID 31703694, 2019). "However, it is worth noting that AQP9 promotes a series of immune responses and tumor environment, which are estimated to be highly expressed in many cancers." (PMID 31703694, 2019).
tumor (continued). "Previous work has suggested that the reduced glycerol levels commonly observed in HCC tumor cells may be related to downregulated expression of the aquaglyceroporin AQP9, which serves as a channel for glycerol and water transport." (PMID 28881813, 2017). "Thus, we can speculate that AQP9 may play a role in not only reducing survival time in tumors but also suppressing the tumor immunity." (PMID 34804972, 2021). "However, the potential mechanisms of AQP9 affecting tumor immune infiltration remained unclear." (PMID 33247170, 2020). "To investigate whether AQP9 expression was associated with chemosensitivity in CRC, we first compared AQP9 mRNA levels in CRC tumor tissues from 16 chemotherapy responders and 16 nonresponders." (PMID 28640255, 2017). "However, in the tumour stem cells and differentiated cells, only aqp9 dominated." (PMID 22262958, 2012). "High expression of Wnt in HCC can increase tumor progression, and aquaporin 9 impairs Wnt/β-catenin to suppress invasion and EMT in tumor cells." (PMID 38334836, 2024). "SETD1A knockdown changed the landscape of SEs, resulting in activation of the transcription of SE-driven tumor suppressors, such as ST3GAL4, AKAP12, PTPN1, AQP9, and ANKRD11." (PMID 37581938, 2023). "In the TCGA-HNSC cohort, we observed the expression of 12 ion channel genes in tumor and normal tissues; ANO1, AQP9, BEST2, CHRNA5, and KCNJ15 were upregulated in HNSCC, while AQP1, AQP5, SCNN1G, and SCN4A were downregulated." (PMID 36389709, 2022). "The increase on AQP9 mRNA and protein levels through dbcAMP modulation was also confirmed in a mice model of HCC, resulting in tumor growth suppression with decrease in tumor size." (PMID 35187089, 2022). "The findings revealed that ANO1, AQP9, and BEST2 were upregulated in tumor tissues, and AQP5, SCN4A, and SCNN1G expression was upregulated in normal tissue from 12 HNSCC patients." (PMID 36389709, 2022). "Immunohistochemistry results also confirmed that AQP9 and ZAP70 expression was significantly lower in tumor tissues relative to normal tissues." (PMID 35477402, 2022). "The results showed that KIAA1429, HAMP, AQP9, CCL13, and CCL21 were significantly negatively correlated with tumor purity, and KIAA1429 was highly correlated with B cells, CD8 T cells, CD4 T cells, macrophages, neutrophils, and dendritic cells." (PMID 34422053, 2021). "Previous studies have suggested that tumor cell sensitivity to ATO is related to the intracellular arsenic content, and aquaporin 9 (AQP9) is the key factor that determines intracellular arsenic content." (PMID 34675983, 2021). "The expression levels of AQP9 were significantly down-regulated in HCC tissues and cells, which was also correlated with tumor size and number, TNM stage, five-year survival rate, lymphatic and distal metastasis within the patients." (PMID 31969493, 2020). "Aquaporin 9 (AQP9), as an aquaglyceroporin, is expressed in many immune cells and plays important role in tumor initiation and progression." (PMID 33247170, 2020). "Further functional study revealed that overexpressed AQP9 was able to inhibit proliferation, migration and invasion of HCC cells via Wnt/β-catenin pathway, and suppressed tumor growth in vivo." (PMID 31969493, 2020). "Protein kinase A activator, dibutyrul cAMP, increased AQP9 expression in HCC cells and suppressed tumor growth in vivo, suggesting the important roles of hepatocyte AQP9 in HCC development." (PMID 27703473, 2016). "The modulation of these genes’ expression was analyzed, according to the age range and gender of the patients and the grade of tumor invasiveness and aggressiveness, and was further correlated with the gene expression of AQP1, AQP3, AQP5, and AQP9, previously reported." (PMID 40305202, 2025). "In the tumor tissue stage, monocytes remain active in the TME, interacting with tumor cells and other immune cells, marked by elevated expression of CXCL8, NAMPT, AQP9, and BCL2A1." (PMID 38720887, 2024).
tumor (continued). "Lower expression of AQP9 and ZAP70 was found in tumor tissues compared to normal tissues." (PMID 35477402, 2022). "Furthermore, by performing mIHC, we preliminarily confirmed that AQP9 presents a relevance with the expression levels of M2 TAM and the recruitment of CD8+ T cells in tumor environment." (PMID 34804972, 2021). "Moreover, AQP9 can also activate RAS signal and sensitize tumor cells to chemotherapy drugs in colorectal cancer." (PMID 33247170, 2020). "KEGG analysis also revealed that genes co-expressed with AQP9 could be involved in immune related pathways in BRCA, COAD, LUAD, LUSC and STAD, which were also correlated to tumorigenesis or tumor progression." (PMID 33247170, 2020). "As a result, the findings further confirmed that AQP9 expression was closely correlated with immune infiltrates in BRCA, COAD, LUAD, LUSC and STAD, which indicated that AQP9 was crucial in immunologic escape and immune tolerance in tumor microenvironment." (PMID 33247170, 2020). "AQP9 expression within tumor parenchyma is not widespread, compared to abundant expression of the related water channel AQP4." (PMID 24086629, 2013). "Furthermore, we compared the expression of AQP9 and ZAP70 in tumor and normal tissues." (PMID 35477402, 2022). "Therefore, we speculate that the interaction between AQP9 and M2 can hinder the recruitment of CD8 T cells and NK cells and ultimately push TME to a tumor-friendly direction." (PMID 34804972, 2021). "Notably, ATRA also induced AQP9 expression and cooperated with ATO to induce Pin1 degradation, destabilization of Pin1’s substrate oncoproteins, and stabilization of Pin1’s substrate tumor suppressors, in both TNBC cell orthotopic and PDOX tumors." (PMID 30093655, 2018). "The transcription regulation of AQP9 has not been thoroughly investigated, and other pharmacological agents may also activate AQP9 gene through various mechanisms to enhance the anti-tumor effects of As2O3." (PMID 25953102, 2015). "We found that larger AQP9 expressing cells were not uniformly present throughout tumor biopsies." (PMID 24086629, 2013). "Moreover the AQP9 immunoreactivity was found to be increased at the tumour border, but not within the tumour." (PMID 21119878, 2010). "The ADCst, ADCslow and ADCuh at tumor center presented correlations with AQP1 and AQP4 while AQP9 did not correlate with any DWI metric." (PMID 34712604, 2021). "According to the GEPIA database, AQP1, AQP3, AQP4, and AQP9 were significantly expressed in LUAD tissues compared to normal lung tissues (p < 0.05), but some genes including AQP0, AQP5, AQP6, AQP7, AQP8, AQP10, and AQP11 were not differentially expressed between tumor and normal tissues." (PMID 34708074, 2021).
cancer (33 papers, 2008 to 2025). A tumor composed of atypical neoplastic, often pleomorphic cells that invade other tissues. "So far, four AQPs (AQP1, AQP4, AQP5, and AQP9) have been linked to EMT in several cancer cell models." (PMID 35847914, 2022). "The ATO-induced cell death is highly associated with expression level of AQP9, and AQP9 expression level varies between different types of cancer cells." (PMID 32010690, 2019). "Of note, at least four AQPs (AQP1, AQP3, AQP4, and AQP9) have been shown to modulate the activity of specific MMPs, which appears to be a key mechanism underlying the promotion of cellular local invasion and cancer cell metastasis by AQPs." (PMID 35847914, 2022). "In order to investigate the potential factors that may affect the AQP9 expression, we explored the association of AQP9 expression levels with relevant gene mutation levels in different cancers via LinkedOmincs database and the promoter methylation levels of AQP9 in UALCAN database." (PMID 33247170, 2020). "It has been shown that AQP9 promotes cancer cell invasion and motility through the AKT signaling pathway." (PMID 40989165, 2025). "In recent years, AQP9 implication in a variety of disorders, including liver injury, inflammation, cancer, and altered immune response, revealed AQP9 as a promising drug target and a diagnostic/prognostic biomarker in clinical medicine." (PMID 35883453, 2022). "Dysregulation of AQP9 is found in a variety of clinical conditions, such as cancer and inflammatory disorders." (PMID 35883453, 2022). "The involvement of AQP9 in glycerol transportation continues to draw attention from researchers, and now it has been extended to cancer research." (PMID 35972604, 2022). "Furthermore, AQP9 was also found upregulated in human glioblastoma probably due to its contribution for energy metabolism and its ability of lactate and glycerol clearance from the extracellular space to counteract the lactate acidosis that is associated with this specific type of cancer." (PMID 35187089, 2022). "Previous research has linked aberrant expression of HS3ST3A1, AQP9, MYLK, and RAB23 to cancer formation, invasion, and prognosis." (PMID 36199571, 2022). "In several cancer cell lines, the expression of AQP9 was related to the uptake of [14C]-labeled glycerol." (PMID 35972604, 2022). "Similar effect was attained with AQP9 knockdown with decrease in cancer aggressiveness, suggesting AQP9 as a promising therapeutic target for RCC." (PMID 35187089, 2022). "Pan-cancer analyses identified that AQP9 was correlated with immune infiltration as well as acted as a prognostic factor in various cancers." (PMID 35477402, 2022). "Accordingly, the cancer-promoting effects and the changes of components in the immune microenvironment are related to the high expression of AQP9, and TME transformations all suggest that AQP9 is related to the malignant degree of KIRC." (PMID 34804972, 2021). "AQP9 mRNA expression level showed a significant difference in various cancer types, while AQP9 showed little difference in protein expression level." (PMID 33247170, 2020). "In the future research, more clinical information should be collected to further investigate the relationship between AQP9 expression and different pathologic characteristics of cancers." (PMID 33247170, 2020). "We chose distinct cancer types whose prognosis correlated significantly with AQP9 expression in Prognoscan and Kaplan–Meier plotter databases." (PMID 33247170, 2020). "Herein, we aimed to elucidate the correlations of AQP9 with prognosis and immune infiltration levels in diverse cancers." (PMID 33247170, 2020). "The results indicated that AQP9 mRNA levels were significantly reduced in HCC tissues compared with paired para-carcinoma controls." (PMID 31969493, 2020). "AQP9 was abundantly expressed on the cell membrane in para-carcinoma tissues, while its expression level was significantly decreased in HCC samples." (PMID 31969493, 2020).